MYD88 (MYD88 innate immune signal transduction adaptor)
Diseases named in the same sentence as MYD88 in open-access papers (continued):
Sharing a sentence is not in itself a finding about the gene and the disease.
Cerebral ischemia (continued). "In summary, this study revealed that SB can protect against cerebral ischemia–reperfusion injury by controlling microglia polarization and microbiome-gut-brain axis to inhibit brain inflammation via the TLR4/MyD88/NF-κB pathway." (PMID 39962509, 2025). "Evobrutinib treatment improves neurological function of mice with cerebral ischemia, and alleviates neuroinflammation by inhibiting M1 microglia polarization through TLR4/Myd88/NF-κB pathway." (PMID 40263985, 2025). "Stimulation of the vagus nerve during the acute stage of cerebral ischemia can inhibit M1-type polarization and promote M2-type polarization by blocking the TLR4/MyD88/NF-κB signaling pathway, leading to improved outcomes in ischemic stroke." (PMID 37361996, 2023). "In cerebral ischemia/reperfusion models for stroke injury, HSP70 binds to TLR4, activating MyD88-IRAK-TRAF6 and NF-κB pathways, with downstream induction of TNFα and other cytokines, as observed for nPM-LPS responses." (PMID 28410596, 2017). "Their findings revealed that lamprophyllin could protect against cerebral ischemia–reperfusion injury by regulating intestinal microbiota, inhibiting TLR4/MyD88/NF-κB inflammatory pathways in the brain, and regulating intestinal CYP3A4 expression." (PMID 40308697, 2025). "In relation to cerebral ischemia, it has been shown that disruption of downstream MyD88-independent (TRIF) TLR pathway does not confer protection in in vitro and in vivo models of cerebral ischemia." (PMID 25886362, 2015). "The detailed mechanism of the protective effects of simple O-substituted isoflavones against cerebral ischemia reperfusion might be related to the PI3K/AKT/ERK/mTOR or GSK-3β pathway, eNOS/Keap1/Nrf-2/HO-1 pathway, TLRs/TIRAP/MyD88/NFκ-B pathway, and Bcl-2-regulated anti-apoptotic pathway." (PMID 36142301, 2022). "The long-term inflammatory response of muscle after cerebral ischemia serves as a key therapeutic target, and HIIT may regulate macrophage polarization via inhibiting the TLR4/MyD88/NFκB signaling pathway, thereby reducing the cytotoxicity and proinflammatory properties of macrophages." (PMID 34845407, 2021). "Thus, we hypothesized that vinpocetine may alleviate cerebral ischemia and reperfusion injury by down-regulating TLR4/MyD88/NF-κB signaling." (PMID 29113305, 2017). "In this study, we found vinpocetine exerts a protective role on a cerebral ischemia and reperfusion model by inhibiting TLR4/MyD88/NF-κB signaling, but not the TLR4/TRIF/NF-κB signaling pathway, in vitro and in vivo." (PMID 29113305, 2017). "Based on these data, vinpocetine inhibits NF-κB activation through the MyD88-dependent signaling pathway, but not the TRIF-dependent signaling pathway, in response to cerebral ischemia/reperfusion injury or OGD." (PMID 29113305, 2017).
parasitemia (26 papers, 2008 to 2024). "Next, we investigated the effect of MyD88 deficiency in infection outcome by comparing parasitemia and survival period of T. congolense-infected WT and MyD88−/− mice." (PMID 31824484, 2019). "Furthermore, MyD88 knockout mice were more susceptible to T. cruzi, with higher parasitemia and greater mortality." (PMID 21869919, 2012). "Moreover, mice deprived of the type I IFN receptor, Ifnar−/−, develop higher parasitemia levels in comparison with control 129Sv mice and doubly deficient Myd88−/−Ifnar−/− mice are highly susceptible to infection with T. cruzi." (PMID 20442858, 2010). "In line with this, we found that deficiency of MyD88 leads to impaired phosphorylation of MAPKs and STATs in macrophages following T. congolense stimulation and this was associated with inability to control the first wave of parasitemia and death within 10 days in the relatively resistant mice." (PMID 31824484, 2019). "These insights underscore the complex interplay between immune regulation and fibrotic processes in the context of parasitic infections, emphasizing the potential therapeutic implications of targeting the MyD88 pathway and modulating Ghrelin levels." (PMID 39749332, 2024). "Infected MyD88−/− mice on the relatively resistant background developed higher and uncontrolled first wave parasitemia compared to WT mice and died within 10 days post-infection." (PMID 31824484, 2019). "Although in transferred Myd88−/− mice parasitemia was decreased to the WT level (as in transferred Il18r1−/−mice) and survival was also significantly delayed, still, the totality of Myd88−/− mice succumbed to infection." (PMID 28895840, 2017). "Both liver parasite burden and blood parasitemia were compared among WT, TLR2-, TLR4- and MyD88-deficient mice following intravenous P. yoelii sporozoite challenge." (PMID 26667391, 2015). "As IL-12 and MyD88 are crucial to protection against parasitic infection, IL-12p40-/-, MyD88-/- and CCR5-/- mice were unsurprisingly highly susceptible to T. gondii infection." (PMID 24086456, 2013). "Arginase 1 is also induced in classically activated (M1) macrophages in a STAT6 independent manner via the Toll–like receptor 2/MyD88 pathway following parasitic infection." (PMID 22629434, 2012). "Furthermore, like the Tmem173gt and Mb21d1–/‐ mice, the Myd88–/– mice presented a markedly reduced late IL‐6 release and reduced parasitemia levels, thus prolonging their survival." (PMID 35635376, 2022). "However, it was possible to note that the MyD88-/- group started to die later, probability due to the augment of parasitemia levels observed from the twentieth day post-infection onward." (PMID 30761111, 2019). "The MyD88 deficiency in cardiomyocytes does not affect the systemic control of the parasite, as similar parasitemia curves were observed in tamoxifen-treated Mer+MyD88flox+/+ and MerCreMer+/+ mice." (PMID 30067739, 2018). "To determine whether MyD88 signaling in cardiomyocytes contributes to systemic T. cruzi control, we compared the parasitemia curves and survival rates of Mer+MyD88flox+/+ and MerCreMer+/+ mice that were both treated with tamoxifen and infected with 5 x 102T." (PMID 30067739, 2018). "Furthermore, the adoptive transfer of WT CD4+ T cells was able to reduce parasitemia to WT levels in both Il18r1−/− and Myd88−/− infected mice, in an IFN-γ-dependent way, and to improve survival in both strain." (PMID 28895840, 2017). "Interestingly, the TLR2 signaling can significantly suppress the development of the pre-erythrocytic stage of Plasmodium yoelii, as both liver parasite load and subsequent parasitemia were significantly elevated in both TLR2- and MyD88-deficient mice." (PMID 26667391, 2015). "Interestingly, the degree of parasitemia exhibited by the NLRP3−/− and caspase-1−/− mice was comparable to that exhibited by the MyD88−/− and iNOS−/− mice, which are considered susceptible models for T. cruzi infection." (PMID 24098823, 2013).
parasitemia (continued). "Th1-type cellular immunity, Myd88/NF-κB and TGF-β1/Smad3 signaling pathways are activated to exert protective effects against parasite infection in the early stage of E. g infection." (PMID 39436864, 2024). "Accordingly, T. brucei infected MyD88 KO mice and IFN-γ KO mice exhibited reduced Tip-DC percentage and reduced production of TNF, correlating with an inability to efficiently control parasitemia." (PMID 20714353, 2010). "In murine models, the control of parasitemia is mostly mediated in the liver by IFN-γ- and MyD88-dependent generation of classically activated monocytic cells (M1) that secrete trypanotoxic molecules TNF and NO and exert phagocytic activity." (PMID 20714353, 2010). "Additionally, the IL-12p40 levels after stimulation with LPS were significantly decreased in both the Trif-/- and Myd88-/- BMDCs compared with the WT BMDCs, which demonstrates the specificity of TLR4 during parasite infection." (PMID 32210480, 2020). "Mice lacking MyD88 were developed in 1998 and have since been used to show the crucial role of MyD88 in resistance to bacterial or parasite infection." (PMID 31695691, 2019). "To verify the impact of the absence of IL-18R- or MyD88-mediated signaling on resistance to infection, we compared parasitemia levels, as well as survival and parasite load in the myocardium, between Il18r1−/−, Myd88−/− and WT (B6) mice." (PMID 28895840, 2017). "(A and C) Survival; (B and D) mean parasitemia levels at day 9 pi of Il18r1−/− (A and B) or Myd88−/− mice (C and D), which received or not 1.3 × 106 CD4+ T cells purified from infected WT B6 mice." (PMID 28895840, 2017). "Together, these results show that while increasing the numbers of IFN-γ+CD4+ T cells in Il18r1−/− mice is enough for restoring their resistance to infection to the WT level, both in terms of parasitemia and survival, this is not the case for Myd88−/− mice." (PMID 28895840, 2017). "At present we do not know why Myd88−/−mice succumb earlier than WT mice and display 100% mortality to T. cruzi infection, notwithstanding their capacity of controlling blood parasitemia and their preserved CD8+ T cell-mediated responses shown here." (PMID 20442858, 2010). "The absence of MyD88 did not impact parasitemia during primary infection with B. microti." (PMID 38392861, 2024). "WT mice presented significantly lower parasitemia when compared to either Il18r1−/− or Myd88−/− mice at day 9 pi, when the peak of parasites in the blood is attained, and no statistical difference in parasitemia levels was found between Il18r1−/− and Myd88−/− mice." (PMID 28895840, 2017). "Although the role of IFNβ in the protection against parasite infection remains controversial, it was demonstrated that IFNβ is responsible for resistance of macrophages infected with T. cruzi mainly in the absence of MyD88." (PMID 21869919, 2012). "Also in accordance with this hypothesis, extensively discussed by us in a previous work, doubly MyD88/TRIF-deficient (as MyD88/IFNAR1 DKO) mice are more sensitive to infection and do not control parasitemia." (PMID 22496959, 2012).
Arthritis (25 papers, 2008 to 2025). Inflammation of a joint. "The pathogenesis of arthritis in A20-deficient murine models is critically dependent on MyD88-mediated innate immune signaling." (PMID 41583484, 2025). "We therefore determined the effects of FcγR deficiency alone or in combination with MyD88 deficiency on B. burgdorferi-induced arthritis." (PMID 24967215, 2014). "Concomitant ablation of MyD88 reversed the effects of mast cell-specific A20 loss during arthritis induction to a large extent, indicating essential roles for IL-33, TLR ligands, and/or IL-1β." (PMID 24453940, 2014). "Our results using mice deficient in FcγR only or in both FcγR and MyD88 reveal that FcγR has a dual role in immune defense and arthritis development associated with B. burgdorferi infection." (PMID 24967215, 2014). "Notably, further knockout of MyD88 in synovial fibroblasts, inhibits arthritis caused by A20 myeloid knockout." (PMID 41583484, 2025). "Additionally, patients with single nucleotide polymorphisms (SNPs) in Myd88, Il1a, and Il1r1 genes have an increased risk of osteomyelitis and inflammatory joint disorders, further underscoring the importance of these immune pathways in skeletal homeostasis." (PMID 30978245, 2019). "Mice deficient in both FcγR and MyD88 had minimal arthritis at this time point." (PMID 24967215, 2014). "To assess the effects of FcγR deficiency on prevalence of arthritis after B. burgdorferi infection, we determined the number of joints that had evidence of inflammation in WT and MyD88−/− mice for comparison with FcεRγ−/− and the double knockout FcεRγ−/− MyD88−/− mice." (PMID 24967215, 2014). "Our study indicates that Rh2-pre Exo can suppress TLR4/Myd88/NF-κB inflammatory signaling, reprogramming macrophages to an anti-inflammatory state and thereby alleviating arthritis in CIA mice." (PMID 40502627, 2025). "The plasmid backbone and multiple immunoregulatory properties of IL-18 appear to play a major role in the pIL-18 coadministration with rIL-4-mediated immunomodulation of arthritis through blocking the TLR2/MyD88/NF-kappa B signaling pathway." (PMID 29854762, 2018). "The plasmid backbone and multiple immunoregulatory properties of IL-18 appeared to play the major role in the pIL-18 coadministration with rIL-4-mediated immunomodulation of arthritis through blocking the TLR2/MyD88/NF-kappa B signaling pathway." (PMID 29854762, 2018). "The severity of arthritis was highest in MyD88−/− mice at day 14, although FcεRγ−/− mice also exhibited a modest increase in joint inflammation relative to WT at this time point." (PMID 24967215, 2014). "MyD88−/− and WT mice exhibited comparable degrees of inflammation in these joints whereas arthritis scores were lower in FcεRγ−/− mice and FcεRγ−/− MyD88−/−." (PMID 24967215, 2014). "We found that arthritis in the knees was completely resolved in the WT and FcεRγ−/− mice and a single joint in one FcεRγ−/− MyD88−/− mouse had a small amount of inflammation." (PMID 24967215, 2014). "In vitro, immune complexes can stimulate MyD88−/− macrophages to produce TNFα, supporting the possibility that FcγR contribute to arthritis in MyD88−/− mice." (PMID 24967215, 2014). "At day 21, WT mice had increased arthritis in comparison to the day 14 timepoint, whereas the arthritis detected in MyD88−/− was less pronounced." (PMID 24967215, 2014). "The reduced levels of arthritis incidence and severity in the FcεRγ−/− MyD88−/− mice correlated with reduced expression of several chemokines and cytokines compared to the three other strains." (PMID 24967215, 2014). "At day 14 of infection, the prevalence of arthritis was higher in MyD88−/− and FcεRγ−/− mice than in WT or FcεRγ−/− MyD88−/− mice." (PMID 24967215, 2014). "FcεRγ−/− mice had the highest arthritis severity scores relative to WT or MyD88−/− mice at 21 days of infection." (PMID 24967215, 2014).
Arthritis (continued). "The strong reduction of arthritis was in line with the findings that the local cytokine production was ablated in both TLR2-, and MyD88-deficient mice." (PMID 23148704, 2012). "It was shown that MyD88 knockout mice infected with live B. burgdorferi displayed more severe arthritis and cell influx as compared to infected WT mice." (PMID 23148704, 2012). "In animal models intra-articular injection of the TLR2 leads to development of destructive arthritis in mice and TLR2/MyD88 knockout mice are protected from SWC induced joint inflammation." (PMID 21858161, 2011). "In experimental animal models, the critical roles of the TLRs and their adaptor molecule myeloid differentiation factor 88 (MyD88) in the development of arthritis have been demonstrated in various models." (PMID 18847495, 2008). "Importantly, K/B × N arthritis clinical severity and inflammatory profile was dependent on IL-1R expression, the essential IL-1R signalling adaptor Myd88, and both the IL-1R ligands, IL-1α and IL-1β." (PMID 25693118, 2015). "In FcεRγ−/− mice, phagocytes may rely on TLR/MyD88-dependent pathways for disposal of B. burgdorferi, with secondary consequences of enhanced inflammatory cytokine secretion and arthritis in the early stages of infection." (PMID 24967215, 2014). "We also show that FcγR may contribute to prolonged arthritis in certain settings, such as in MyD88−/− mice when phagocytosis is impaired and pathogen burden is high." (PMID 24967215, 2014). "Cxcl13 may mediate recruitment of immune cells to infected joints during infection, but since the MyD88−/− mice (which have reduced expression of Cxcl13) still develop arthritis, this suggests that other chemokines may also play significant roles." (PMID 24967215, 2014). "In contrast, in later stages of infection when disease is resolving, our results suggest that FcγR may promote arthritis in MyD88−/− mice, as elimination of activating FcγR in MyD88−/− mice significantly attenuates this disease manifestation." (PMID 24967215, 2014). "As deficiency in TLR2 or its intracellular signaling molecule MyD88 is sufficient to eliminate B. burgdorferi lipoprotein-induced innate immune cell activation, the observation that arthritis still occurs in TLR2- and MyD88-deficient mice suggests involvement of other inflammatory pathways." (PMID 24967215, 2014). "While the elevated pathogen burdens seen in B. burgdorferi-infected MyD88−/− mice were not affected by concomitant deficiency in FcγR, arthritis was reduced in FcεRγ−/−MyD88−/− mice in comparison to wild type or single knockout mice." (PMID 24967215, 2014). "In addition, MyD88−/− mice express higher levels of the anti-inflammatory cytokine IL-10, which could also lead to reduced arthritis in the setting of elevated pathogen burdens." (PMID 24967215, 2014). "Taken together, our results demonstrate a role for FcγR-mediated immunity in limiting pathogen burden and arthritis in mice during the acute phase of B. burgdorferi infection, and further suggest that this pathway contributes to the arthritis that develops in B. burgdorferi-infected MyD88−/− mice." (PMID 24967215, 2014). "Knockout models using B6 TLR2−/− or MyD88−/− mice have shown the important role of NF-κB in host defense, but because these mice have such a severe innate defect in bacterial defense, elucidating the role of NF-κB in arthritis using these models has remained difficult." (PMID 24967703, 2014). "This was not the case with MyD88−/− mice, which had the highest prevalence of arthritis, with 8 of 10 knees showing some degree of inflammation." (PMID 24967215, 2014). "Additionally, the same study showed that MyD88 is a key molecule and confirmed the essential role of IL-1 since no arthritis was observed in either MyD88- or IL-1R KO mice." (PMID 27313578, 2016).
Arthritis (continued). "Furthermore, MyD88 and TRIF inhibitors inhibited LPS-induced production of IL-12p35 in joint cells from WT mice with arthritis as compared with cells treated with a control peptide, indicating that LPS-mediated IL-12p35 production during antibody-induced arthritis depends on MyD88 and TRIF." (PMID 23036692, 2012). "While the TLR/MyD88 signaling pathway is the main pathway contributing to B. burgdorferi lipoprotein mediated inflammation in vitro, arthritis and carditis still develop in vivo in the absence of TLR2 or MyD88 expression." (PMID 24967215, 2014).